TRPC1 (transient receptor potential cation channel subfamily C member 1)
Diseases named in the same sentence as TRPC1 in open-access papers (continued):
Sharing a sentence is not in itself a finding about the gene and the disease.
breast carcinoma (continued). "The scenario becomes even more complicated when considering that Orai3 is activated by Stim1 upon intracellular store depletion in some oestrogen receptor-positive breast cancer lines, and that Orai1 may assemble into a supramolecular ternary complex with Stim1 and TRPC1." (PMID 25126575, 2014). "Moreover, several isoforms of TRPC channels, dependent on the cell type, have been implicated in the CaSR activation-induced Ca2+ entry, such as TRPC3 in salivary ductal cells, TRPC1 in MCF-7 breast cancer cells and keratinocytes, and TRPC6 in aortic smooth muscle cells and cardiac myocytes." (PMID 24905090, 2014). "Therefore, we assessed whether TRPC1-mediated inhibition of constitutive ERK1/2 activity in MDA-MB-468 breast cancer cells led to reduced cell count and S-phase reduction." (PMID 22666335, 2012). "PEMF therapy was also previously shown to enhance breast cancer cell vulnerability to DOX in vitro and in vivo that correlated with TRPC1 expression and mitochondrial respiratory rates." (PMID 39594815, 2024). "We demonstrate that the vulnerability of breast cancer to PEMF and DOX therapies is positively correlated with TRPC1 expression as are invasiveness and EMT, conferring upon them a heightened level of specificity for TRPC1-characterized cancers." (PMID 35141145, 2021). "Several studies found that TRPC1 promotes breast cancer cell proliferation and facilitates TGFβ-induced epithelial-mesenchymal transition (EMT), suggesting that TRPC1 is an essential signal for breast tumor growth and metastasis." (PMID 32211326, 2020). "In the case of MDA-MB-468 breast cancer cells, hypoxia-induced induction of ORAI3 is mediated by HIF1α, placing ORAI3 alongside TRPC1 as a HIF1α-inducible ion channel in this model." (PMID 30754719, 2019). "Breast cancer cells from the different subtypes undergo remodeling of the expression of specific molecular SOCE components, including Orai1, Orai3, TRPC1 and even TRPC6." (PMID 30558192, 2018). "Some of these studies have reported that TRPC1, TRPC6 and TRPM7, members of TRP channel family, are involved in cell proliferation as well as in regulating Ca2+ entry in breast cancer." (PMID 27183905, 2016). "Together these results strongly suggest that TRPC1 is the major Ca2+ entry channel that regulates TGFβ-induced EMT and its expression is increased in breast cancer tissues." (PMID 27793015, 2016). "TRPC1, TRPM7 and TRPM8 expression strongly correlated with proliferative parameters, and TRPV6 was mainly overexpressed in invasive breast cancer cells." (PMID 22692672, 2012). "To explore the possible consequences of TRPC1-mediated reductions in ERK1/2 signaling, we assessed cell proliferation in MDA-MB-468 breast cancer cells with TRPC1 silencing." (PMID 22666335, 2012). "In this regard, it was shown that moderately strong magnetic field exposure selectively induced cell cycle arrest in breast cancer cells, but not in healthy cells, in a manner that was predicted by TRPC1 expression." (PMID 39594815, 2024). "Importantly, analogous PEMF exposure of breast cancer cells potentiated the anti-cancer effects of DOX in vitro, ex vivo and in vivo, revealing a synergistic relationship between PEMFs, TRPC1 expression and DOX treatment." (PMID 39594815, 2024). "For example, expression of TRPC1 in breast cancer tissue is higher than that in adjacent normal tissue, in which TRPC1 is increased in colorectal cancer (CRC) tissues compared with adjacent normal tissues." (PMID 35548183, 2022). "For instance, TRPC1 modulates the phosphatidylinositol 3-kinase/protein kinase B (PI3K/AKT) pathway and epithelium-mesenchymal transformation (EMT), subsequently influencing cell proliferation and migration of breast cancer cells." (PMID 35548183, 2022). "Increased Ca2+ through TRPC1, TRPM7/8, P2X7, and SOCC enhances breast cancer cell migration." (PMID 33806911, 2021).
breast carcinoma (continued). "However, TRPC1 expression was reported to be upregulated in basal-like breast cancer cells and closely related to epithelial-to-mesenchymal transition (EMT); moreover, high TRPC1 expression was shown to be predictive of poor prognosis." (PMID 33854967, 2021). "Considering TRPC1 in osteoclasts is inactivated in physiological conditions and required for EMT in breast cancers, it will be interesting to examine whether TRPC1 is activated when bone metastasis is occurred in breast cancers." (PMID 32211326, 2020). "There are numerous studies showing a clear correlation between cancer patient survival and TRP channel expression, e.g., TRPC1, TRPM2 and TRPV4 in breast cancer, TRPM7 in PDAC, TRPM8 in bladder cancer and osteosarcoma and TRPV2 in breast and esophageal cancer to name just a few examples." (PMID 29772843, 2018). "For instance, an increase in Stim1 and Orai1 transcripts and proteins has been described in oestrogen receptor-negative human breast cancer cell lines, while TRPC1 up-regulation in these cells is still controversial." (PMID 24603752, 2014). "No significant up regulation of TRPC1 was found in the breast cancer tissues compared to the normal tissues (F = 5.3 p = 0.069 n = 5)." (PMID 19689790, 2009). "Importantly, muscle cells appear to be less sensitive than breast cancer cells to DOX-mediated cytotoxicity when administered in conjunction with magnetic exposure, possibly reflecting inherently lower expression levels of TRPC1 in healthy muscle." (PMID 39594815, 2024). "Agonist-evoked Ca2+ signals through the activation of Orai1 also fine tune breast cancer cell functions as described in triple negative breast cancer cells where progesterone attenuates cell proliferation by a mechanism involving Ca2+ entry mediated by STIM2, Orai1, and TRPC1." (PMID 33916304, 2021). "Additionally, EGF-stimulated EMT, which transforms breast cancer MDA-MB-468 cells into a mesenchymal-like shape, increases the expression of ATP-binding cassette subfamily C member 3 (ABCC3) after Ca2+ signaling of TRPC1." (PMID 33806911, 2021). "Analysis of the gene expression profile of TRPC1 in breast cancer-derived cell lines has reported that TRPC1 is modestly up-regulated in basal cell lines (including the representative MDA-MB-231 cells) compared with breast cancer cell lines of different subtypes or non-tumoral breast cell lines." (PMID 30558192, 2018). "However, changes in TRPC1 expression level during the cell cycle progression of breast cancer cells have never been reported." (PMID 27183905, 2016). "KCa3.1 and TRPC1 mRNA and protein levels have previously been shown to be higher in breast cancer than in matched normal tissue, but this was a single patient series without information on clinical and pathological breast cancer parameters or patient survival." (PMID 27183905, 2016). "Taken together, these data suggest that TRPC1 expression may play a role in facilitating EMT and proliferation, and further studies are required to carefully delineate the mechanism underpinning the role of TRPC1 in mediating EMT and proliferation in breast cancer." (PMID 32046188, 2020). "Unlike TRPC1 and TRPC6, TRPC5 has been identified to mediate chemotherapeutic resistance in breast cancers." (PMID 32211326, 2020). "Therefore, the non-stimulated Ca2+ influx observed in MDA-MB-468 breast cancer cells, which is sensitive to both TRPC1 and ORAI1 knockdown, may be due to enhanced ER Ca2+ leak through TRPC1, the consequence of which is increased store-regulated Ca2+ influx through ORAI1." (PMID 22666335, 2012). "Here we show that in MDA-MB-468 breast cancer cells, both ORAI1 and TRPC1 silencing reduce non-stimulated Ca2+ influx; suggesting that altered activity of these channels may be a feature of EGF-induced EMT." (PMID 22666335, 2012).
cardiac hypertrophy (25 papers, 2009 to 2025). "In rats with hyperthyroidism-induced cardiac hypertrophy, increased TRPC1 activation was linked to the deterioration of Ca2+ balance contributing to the hypertrophic remodeling." (PMID 36620209, 2022). "Another recent study suggests a combined activity of TRPC4 with TRPC1 causing a background Ca2+ entry, which causes an elevation of diastolic and systolic Ca2+ levels and induces reactive signaling and cardiac hypertrophy." (PMID 27992507, 2016). "Although they identified an increased leak-like current in WT cardiomyocytes after application of TAC which is missing in TRPC1-deficient cells, it is rather unlikely that TRPC1 alone is responsible for cardiac hypertrophy." (PMID 25268281, 2014). "In contrast to WT mice, TRPC1-deficient mice fail to develop maladaptive cardiac hypertrophy." (PMID 25268281, 2014). "As TRPC1 has been implicated in the promotion of mammalian cardiac hypertrophy it may be implicated in temperature-induced cardiac hypertrophy in fish." (PMID 20479879, 2010). "There is evidence that other canonical subunits are involved in cardiac hypertrophy, most notably Ca2+ influx through TRPC1, TRPC3, and TRPC6 channels initiates the calcineurin-NFAT hypertrophy signalling pathway." (PMID 38672459, 2024). "Conversely, overexpression of TRPC1 induced cardiomyocyte hypertrophy, showing that TRPC1 is sufficient to induce cardiac hypertrophy." (PMID 36620209, 2022). "As a body of literature covers its involvement in cardiac hypertrophy, the role of TRPC1 in maladaptive cardiac remodeling can be reviewed in the context of our results here." (PMID 36620209, 2022). "Silencing of TRPC1 in NRVMs with siRNA has been shown to prevent cardiac hypertrophy induced by endothelin-1, angiotensin-II, and phenylephrine." (PMID 36620209, 2022). "TRPC1 is well-established to play a critical role in the development of cardiac diseases including heart failure and hypertrophy." (PMID 36620209, 2022). "When the TRPC1 gene was silenced, it resulted in inhibition of nicotinamide phosphoribosyl transferase -induced cardiac hypertrophy." (PMID 33754657, 2021). "Cardiac hypertrophy is also observed in rat heart tissue as early as one week post I/R, which correlates with the upregulation of the expression of TRPC1, 3, 4, 5, and 6 mRNA and the activation of the fetal gene program (unpublished data)." (PMID 31936700, 2020). "Both mRNA and protein expression levels of TRPC1 are increased in the hearts of cardiac hypertrophy model rats." (PMID 32079284, 2020). "Functionally, TRPC1 is involved in cardiac hypertrophy, hypertension, vascular inflammation and cancer." (PMID 29549288, 2018). "Studies on transient receptor potential channels revealed that the upregulation of TRPC and TRPV subfamilies contributes to the pathophysiology of vascular and cardiac tissues, with direct implication of increased TRPC-1 levels in cardiac hypertrophy." (PMID 30340421, 2018). "In an induced rat-heart hypertrophy model, the expression of TRPC1 rises in the hypertrophic myocardium." (PMID 26778915, 2014). "TRPC1 down-regulation by specific siRNAs attenuated cardiac hypertrophy and the Trpc1 gene has conserved NFAT consensus sites in its promoter region." (PMID 25268281, 2014). "TRPC1 has been demonstrated to be involved in the formation of SOC that contributes to the development of cardiac hypertrophy." (PMID 20003325, 2009). "In conditions such as cardiac hypertrophy or arrhythmia, the synergisticeffect of TRPC1 with CRAC channels enhances calcium influx, resulting inprolonged action potentials and spontaneous calcium release, thereby promotingelectrical remodeling in the myocardium." (PMID 40630446, 2025). "Understanding the mechanism of STIM1, Orai1 and TRPC1 may prevent cardiac hypertrophy or heart failure." (PMID 35303866, 2022). "Blocking or suppressing the expression of TRPC1 was sufficient to attenuate cardiac hypertrophy." (PMID 36620209, 2022).
cardiac hypertrophy (continued). "Upregulation of TRPC1 contributed to the development of cardiac hypertrophy." (PMID 35008591, 2021). "From this point of view, silencing of the TRPC1 gene may play a protective role in the prevention of cardiac hypertrophy." (PMID 33754657, 2021). "In addition, the involvement of TRPC1 in cardiac hypertrophy was demonstrated in human embryonic stem cell derived cardiomyocytes." (PMID 32079284, 2020). "Also, they detected a significant correlation of the gene expression of TRPC1 and MEF2c (myocyte enhancer factor 2c), considered a key transcription factor for cardiac hypertrophy." (PMID 31936700, 2020). "In addition to these animal model studies, patients with cardiac hypertrophy or heart failure showed increased expression of TRPC1 mRNA." (PMID 32079284, 2020). "In addition, several experiments demonstrated that TRPC1 plays a critical role in neurohumoral-factor-induced cardiac hypertrophy in vitro." (PMID 32079284, 2020). "Moreover, it has been reported that TRPC1/5 dysregulation contributed to myocardial hypertrophy." (PMID 35303866, 2022). "Furthermore, an in vitro study demonstrated that elevated serotonin levels activated 5-HT2A receptors expressed in cardiomyocytes to worsen cardiac hypertrophy through the transient receptor potential canonical 1 (TRPC1) channel and calcineurin/NFAT signalling pathway." (PMID 34645867, 2021). "Furthermore, lower-expression of miR-19a-3p may enhance the expression of MEF2A, β-MHC, BNP and TRPC1 in cardiomyocyte hypertrophy, which seemingly implies that lower-expression of miR-19a-3p mediated MEF2 signaling might be a cause of myocardial hypertrophy." (PMID 29549288, 2018). "Within the TRPC subfamily, TRPC1, TRPC3, and TRPC6 play key roles incardiac contraction, myocardial hypertrophy, and arrhythmogenesis through theregulation of calcium influx." (PMID 40630446, 2025). "They conclude that “TRPC1 channels are critical for adaptation to biomechanical stress and TRPC dysregulation leads to maladaptive cardiac hypertrophy and failure”." (PMID 24232452, 2013). "Mice with TRPC1 gene deletion maintained preserved cardiac function and failed to manifest evidence of maladaptive cardiac hypertrophy following pressure overload-induced hypertrophy via transverse aortic constriction." (PMID 36620209, 2022). "The current study showed a reduced expression of Rcan1 and enhanced cardiac remodeling in the absence of Orai, whereas reduced Rcan1 expression in the absence of TRPC1/TRPC4 led to a decrease in the development of cardiac hypertrophy." (PMID 32354146, 2020). "The non-specific ion channel TRPC1 (Trpc1) conducts both Ca2+ and Na+ and has been found to be an important regulator of cardiac hypertrophy." (PMID 30914453, 2019). "Considering the role of TRPC3/6 heterotetramer channels in cardiac hypertrophy, TRPC6 protein signaling complex, including TRPC1 and TRPC3, may function as mechano-activated cation channels in the cardiovascular system." (PMID 28936433, 2017). "TRPC1-knockout mice showed no cardiac hypertrophy after transverse aortic constriction." (PMID 32079284, 2020). "Other researchers also convincingly demonstrated an involvement of TRPC3 and TRPC6 and transgenic mice expressing dominant-negative forms of TRPC3, TRPC6 and TRPC4, which will also inhibit TRPC1 heteromeric, but not homomeric, channels are almost completely protected from cardiac hypertrophy." (PMID 25268281, 2014). "For the first time, we discovered that SFI could attenuate myocardial hypertrophy, probably through up-regulating or maintaining the miR-19a-3p level, decreasing MEF2A mRNA and protein expressions, and regulating the protein expression of β-MHC, BNP and TRPC1 of the MEF2 signaling pathway." (PMID 29549288, 2018). "Also, the lack of TRPC1 function in the heart resulted in reduced calcineurin/NFAT signaling, prevented pathological cardiac hypertrophy but preserved contractility." (PMID 27992507, 2016).
glioma (21 papers, 2013 to 2026). A benign or malignant brain and spinal cord tumor that arises from glial cells (astrocytes, oligodendrocytes, ependymal cells). "A loss of function of TRPC1, mediated by pharmacological or genetic inhibition, was found to reduce the proliferation of multinucleated glioma cells, mainly due to the suppression of store-operated Ca2+ entry (SOCE)." (PMID 37892239, 2023). "TRPC1 channels have been found to promote glioma cell migration through their association with focal adhesion proteins and cytoskeletal rearrangement." (PMID 37892239, 2023). "TRPC1 was implicated in glioma cell migration in response to growth factors EGF (epidermal growth factor) and PDGF (platelet-derived growth factor)." (PMID 36768856, 2023). "Stimulation with EGF was associated with a re-localization of TRPC1 channel at the leading edge of migrating D54MG glioma cells within lipid rafts, specialized membrane microdomains enriched in cholesterol and sphingolipids." (PMID 33928077, 2021). "Similar morphological changes have been associated with high invasiveness observed in human glioma cells, which is induced by Ca2+ entry via TRPC1 and activated Cl− currents." (PMID 32963700, 2020). "Like NHE1 or NCKK, TRPC1 channels were localized to lipid raft domains at the leading edge of migrating glioma cells, and shRNA-mediated TRPC1 knockdown resulted in loss of EGF-induced glioma cell migration." (PMID 25852478, 2015). "Additionally, calcium-permeable channels, like TRPC1, are implicated in glioma cell signaling and could be targeted to disrupt tumor growth." (PMID 39202716, 2024). "In this study, we demonstrate that TRPC1 promotes glioma cell migration by increasing Signal transduction and transcription activator 3 (STAT3) protein levels." (PMID 41787243, 2026). "Calcium-permeable channels, like transient receptor potential canonical (TRPC1) channels and calcium-activated potassium channels, are critical in glioma cell signaling, proliferation, and migration." (PMID 39202716, 2024). "Overall, current studies support an EGF-dependent role of TRPC1 on glioma on migration via chemotactic attraction toward EGF, while basal glioma cellular motility does not seem to be TRCP1 dependent." (PMID 36768856, 2023). "Several TRP channels have been studied as potential biological markers of glioma progression and prognosis, including TRPC1, TRPC6, TRPM2, TRPM3, TRPM7, TRPM8, TRPV1/2." (PMID 36768856, 2023). "There is a growing consensus that TRPV1, TRPV2, TRPM2, TRPM3, and TRML1 exert anti-tumorigenic properties in glioma, while TRPC1, TRPC6, TRPM7, TRPM8, and TRPML2 promote glioma growth and proliferation." (PMID 36768856, 2023). "TRPC1 channels, acting as Ca2+-permeable channels, have been shown to regulate Ca2+ influx in glioma cells." (PMID 37892239, 2023). "Knock-down of TRPC1 clearly suppressed cell proliferation and decreased tumor volume by 40% in a xenograft model using human grade IV glioma D54MG cells." (PMID 36033489, 2022). "TRPC1 activation in response to EGF-induced chemotaxis regulates Cl− channel activity in glioma cells in a calcium-dependent manner." (PMID 36497413, 2022). "In our present study, the results showed that the expression of TRPC1 and TRPC3 was significantly increased in glioma with IDH mutation status and 1p/19q codeletion status, while the expression of TRPC6, MCOLN1, MCOLN2, and MCOLN3 was significantly decreased." (PMID 35625048, 2022). "Higher levels of TRPC1, TRPC3, and TRPC5 were significantly associated with longer OS time in glioma." (PMID 35625048, 2022). "A study reported that TRPC1 channels expressed in human glioma cells as well as glioblastoma biopsies." (PMID 36033489, 2022). "In agreement, it has been shown that both TRPC1 channel activity and lipid raft integrity were required for gliomas chemotaxis." (PMID 33928077, 2021).